RNU6-1332P (RNA, U6 small nuclear 1332, pseudogene)
Gene: Small nuclear RNA gene on chromosome 15 (44,962,830 to 44,962,933, forward strand). Ensembl gene ENSG00000252475.
Homologues: Orthologues: chimpanzee U6 (99% identical), mouse Gm23191 (91% identical), macaque U6 (89% identical). Paralogues in human: RNU6-1108P (98% identical), RNU6-12P (92% identical), RNU6-13P (92% identical), RNU6-32P (92% identical), RNU6-41P (92% identical), RNU6-1 (91% identical), RNU6-116P (91% identical), RNU6-15P (91% identical), RNU6-17P (91% identical), RNU6-18P (91% identical), RNU6-2 (91% identical), RNU6-39P (91% identical), and 1289 more.